IL6 (interleukin 6)
Diseases named in the same sentence as IL6 in open-access papers (continued):
Sharing a sentence is not in itself a finding about the gene and the disease.
atherosclerosis (continued). "The resultant inflammasome releases upstream inflammatory cytokines such as IL-1β that activate inflammatory cells and produce IL-6, which stimulates the production of CRP, amplifying the inflammatory cascade and promoting atherosclerosis." (PMID 36558530, 2022). "NF-kappa B promotes the expression of proinflammatory cytokines (such as IL-1, IL-6, and TNF-α) and various atherosclerosis-related genes (including VCAM-1, tissue factor, VEGF, and RAGE)." (PMID 35845584, 2022). "Similar to the pathological process of atherosclerosis, the initiation phase of CAVD involves chemotactic action mediated by cytokines such as TNFα, IL-1β, and IL-6 to activate and recruit immune cells to valve tissue." (PMID 36589450, 2022). "Naringenin can directly or indirectly regulate cytokines such as TNF-α, IL-6, IFN-γ, and signalling pathways NF-kappa B and MAPK and has a relieving effect on atherosclerosis." (PMID 35845584, 2022). "Others have demonstrated that IL-6 and TNF-a become elevated in PAD patients after exercise treadmill testing, suggesting that inflammatory markers increase in conditions of atherosclerosis and hemodynamic stress." (PMID 36582735, 2022). "Inflammatory factors IL-6 and TNF-α play an essential role in all the stages of atherosclerosis, including plaque formation, progression, and rupture." (PMID 34867337, 2021). "IL-6, which is induced by pro-inflammatory cytokines such as IL-1 and TNF cytokines, acts as a central hub for atherosclerosis inflammatory signaling." (PMID 34071276, 2021). "It is well-established that IL-6 was an important inflammatory factor, and MCP-1 and ICAM were immunocyte adhesion factors in atherosclerosis." (PMID 34957248, 2021). "Activated macrophages produce a series of inflammation-related factors such as interleukin-1β (IL-1β), TNF-α, interleukin-6 (IL-6), IL-8, MCP-1, matrix metalloprotease-9 (MMP-9), and so on, which initiate inflammation to induce atherosclerosis." (PMID 34869592, 2021). "It was shown thatthe pro-inflammatory cytokines such as IL-6, IL-1βand TNF-α, can induce VSMCs migration/proliferationand hypertrophic response, which can take part in theexpansion of atherosclerosis." (PMID 34096220, 2021). "It has been reported that STS can reduce the expression of the inflammatory cytokines IL-6 and TNF-α in a mouse model of atherosclerosis." (PMID 34122723, 2021). "Plasma IL-6 levels are used as a marker for CVD such as coronary artery disease and atherosclerosis." (PMID 33786327, 2021). "For instance, IL-6 stimulates AGT, FBG, CRP, SAA and several complement factors’ synthesis that propagate the downstream inflammatory response responsible for atherosclerosis." (PMID 33407555, 2021). "Previous studies have reported elevated levels of IL-6 and CRP in pathologies with low-grade inflammatory status, such as proteinuric diabetic nephropathy, or atherosclerosis and cardiovascular morbidity." (PMID 34064366, 2021). "Atherosclerosis and PAH have the same pathophysiological processes, such as endothelial dysfunction and increased inflammatory mediators such as IL-6." (PMID 34575848, 2021). "hs-CRP is mainly produced under the influence of IL-6, and the literature evidence suggests that hs-CRP is correlated with the pathophysiology of atherosclerosis and coronary artery disease (CAD)." (PMID 34803676, 2021). "Here, we demonstrated that elevated Hcy inhibits the expression of miR‐195‐3p, which in turn enhances IL‐31 expression and thereby causes the secretion of macrophages pro‐inflammatory factors IL‐1β, IL‐6 and TNF‐α and accelerate atherosclerosis." (PMID 34592792, 2021). "IL-6, the highest ranked gene in the PPI network, was significantly downregulated in cytokine-cytokine receptor interaction and lipid and atherosclerosis signaling pathways." (PMID 34880901, 2021).
atherosclerosis (continued). "The inflammatory responses in atherosclerosis are mainly developed through the NLRP3 inflammasome, interleukin‐1 beta (IL‐1β) and interleukin‐6 (IL‐6) inflammatory response axis and eventually lead to an increase in the C‐reactive protein (CRP)." (PMID 34312998, 2021). "Clinical studies report that smokers also have an increased expression of pro-inflammatory markers including IL-6, CRP, E-selectin, P-selectin, and intercellular adhesion molecule-1, all of them well-known players in the pathogenesis of atherosclerosis." (PMID 34440753, 2021). "Infection by Chlamydia pneumoniae, which is suggested to be one of the etiologic agents of atherosclerosis, stimulates the secretion of inflammatory cytokines (TNF-α, IFN-γ, IL-6, etc.) and leukocyte adhesion molecules." (PMID 34959604, 2021). "Regular endurance exercise has been shown to reduce biomarkers associated with chronic, vascular inflammation and the development of atherosclerosis such as tumor necrosis factor alpha (TNF-α), interleukin 6 (IL-6) and C-reactive protein (CRP)." (PMID 34571843, 2021). "IL-6 induces the up-regulation of STAT3 in endothelial cells, which is the key factor to activate endothelial dysfunction and induce atherosclerosis." (PMID 33456354, 2021). "Our former and current data suggest that the IL6 trans-signaling pathway is mainly associated with atherosclerosis related cerebrovascular disease as we could not demonstrate an association with the risk of AF or an increased risk of ischemic stroke in subjects with AF." (PMID 34372806, 2021). "Elevated IL-6 functions in an autocrine manner to further accelerate inflammatory responses in VSMC, thereby making the vasculature prone to atherosclerosis and a less contractile phenotype." (PMID 34504640, 2021). "As the main transcription factor of the inflammatory response, NF-кB can be activated by IL-6, TNF-α, CRP, and so on, which participates in the whole process of atherosclerosis." (PMID 34568579, 2021). "NETs license macrophages to turn on transcriptional regulation of IL-6 and pro-IL-1β via TLR2/4 in atherosclerosis." (PMID 34250033, 2021). "IL-6, which is highly expressed in atherosclerotic aortas, can directly activate gp130/JAK/STAT3 signaling to exacerbate atherosclerosis." (PMID 32169038, 2020). "Here, we found that compared with the Control group mice, serum levels of TNF-α, IL-1β, IL-6 were significantly increased, and IL-10 and ADPN levels were significantly decreased in HFD-induced atherosclerosis mice (Model group; all p < 0.001)." (PMID 32231564, 2020). "Activation of the TLR signaling pathway lead to the production of multiple pro-inflammatory cytokines (IL-6, TNF-α), accelerating the pathological process of atherosclerosis." (PMID 33425996, 2020). "Briefly, as atherosclerosis progresses, increased secretion of tumor necrosis factor (TNF)-α and IL-1 induces production of IL-6 in activated monocytes and vascular smooth muscle cells, which enhances hepatic CRP synthesis." (PMID 32433661, 2020). "In a previous study, we found that the ablation of galectin-12 decreased the secretion of MCP-1, TNF-α, and IL-6 in lipopolysaccharide (LPS)—and saturated fatty-acid-stimulated macrophages, suggesting that galectin-12 may potentially play a role in the pathogenesis of atherosclerosis." (PMID 32752134, 2020). "Inflammation plays a central role in the pathogenesis of atherosclerosis; elevated levels of C-reactive protein (CRP), interleukin-6, and N-terminal pro-hormone B-type natriuretic peptide (NTproBNP) correlate closely with cardiac events." (PMID 33390933, 2020). "Notably, these two conditions are associated with increased levels of C-reactive protein, interleukin-6, plasmin-antiplasmin complex, factor VII, and factor VIII, which by inducing inflammation and hypercoagulability may further promote atherosclerosis progression and thrombosis." (PMID 32397347, 2020).
atherosclerosis (continued). "Our findings are in line with previous research and further confirm the systemic effects of CCL4 antibody treatment on circulating IL-6 and TNF-α in in vivo experimental atherosclerosis." (PMID 32911750, 2020). "IL-1β, IL-6, IL-18, c-reactive protein (CPR), tumor necrosis factor α (TNF-α), etc., as important proinflammatory factors in the process of atherosclerosis, play an important role in promoting the formation of atherosclerosis." (PMID 32733941, 2020). "Therefore, we examined whether a reactive dicarbonyl scavenger could block the pro-inflammatory cytokine response of peritoneal macrophages to ox-LDL, as reflected by reduced mRNA levels of IL1β and IL-6, which are relevant to the development of atherosclerosis." (PMID 32629758, 2020). "The vicious cycle created between OxLDL macrophage activation, TNF-α and IL-6 macrophage secretion, and MCP-1-macrophage recruitment greatly boosts the development of atherosclerosis." (PMID 32752134, 2020). "IL-6 protein was colocalized in plaque with CD68 staining, suggesting that plaque macrophages produce this cytokine during atherosclerosis development." (PMID 33374145, 2020). "It shows antioxidant properties against LDL-oxidation, thus potentially preventing atherosclerosis, and anti-inflammatory properties by decreasing the expression of TNF-α, interleukins IL-6 and IL-1b in a mouse macrophage cell line." (PMID 33237940, 2020). "We focus on the contribution of cytokine networks encompassing IL-4, IL-6, IL-9, IL-17A, IL-33 but also IFN-γ and TNF-α to vascular dysfunction in atherosclerosis." (PMID 32194407, 2020). "NF-kB, SIRT1 and systemic inflammation factors including hs-CRP, IL-6 and TNF-α accelerate atherosclerosis pathogenesis." (PMID 31901246, 2020). "Previous studies in HFD-induced atherosclerosis mice reported that BBR administration remarkably reduced the mRNA expression of pro-inflammatory cytokines, including TNF-α, IL-1β, and IL-6, in ileal and carotid arteries." (PMID 32231564, 2020). "Up-regulation of miR-9 reduced aortic plaque area, the proliferation of collagen fibers, Mac-3-labeled macrophages and levels of IL-6, IL-1β, and TNF-α by suppressing SDC2 and the FAK/ERK signaling pathway, thereby ameliorating atherosclerosis in ACS mice." (PMID 32765295, 2020). "A central component of this is the ability of SOCS3 to limit IL-6 signalling and thus protect against NIH and CABG restenosis, and other inflammatory diseases such as atherosclerosis." (PMID 30719343, 2019). "Interleukin (IL)-6 and high-sensitive C reactive protein (hsCRP) have been shown to be independent predictors of CV disease and ongoing research is directed to test the hypothesis that targeting chronic inflammation could prevent atherosclerosis progression and reduce CV events." (PMID 31110500, 2019). "IL-6 and TNF-α can also induce the production of suPAR from monocytes and lymphocytes, which has a well-established role in the development of atherosclerosis." (PMID 30820636, 2019). "Similar to the function of IL-6, TNF-α is also a pro-atherosclerotic cytokine and increases the development of atherosclerosis in several ways." (PMID 31616435, 2019). "The anti-oxidant N-acetylcysteine (NAC) not only suppresses IL-6 production and VSMC pathological responses including migration and proliferation but also prevents atherosclerosis in ApoE−/− mice." (PMID 31817202, 2019). "Dysregulated cellular functions resulting from IL-6 production induce SMC migration and deposition of ECM, leading to the development of neointimal hyperplasia in atherosclerosis." (PMID 31292433, 2019). "During atherosclerosis, pro-inflammatory cytokines such as TNF-α and IL-6 both have been related to vascular inflammation." (PMID 31780924, 2019). "We demonstrated that LCZ696 or valsartan treatment attenuated the expressions of pro-inflammatory cytokines, including IL-6, MMP-8 and MCP-1, suppressed atherosclerosis and increased plaque stability." (PMID 31019233, 2019).
atherosclerosis (continued). "This is achieved by releasing chemokines and cytokines that include IL-1, IL-6, TNF-α, IFN-γ, and, by producing ROS, growth factor and VSM cell proliferation, thus accelerating the development of atherosclerosis." (PMID 31354915, 2019). "Therefore, IL-6 measurement may have clinical utility as a predictive marker for atherosclerosis." (PMID 31906008, 2019). "Changes in IL-6 and APN levels can reflect both the severity of atherosclerosis and thrombosis and the dynamic process of CVD." (PMID 31191115, 2019). "Ten key regulated genes (including Pla2g2f, Il1f9, Col1a1, Col1a2, and Col3a1 in the brain, while SELP, SELE, IL6, and IL1A in the myocardium, and Tnfrsf12a in both) are correlative with atherosclerosis signaling and inflammatory response." (PMID 29681850, 2018). "The higher levels of cytokines in CAE, particularly IL-6, IL-8, IFN-γ, IL-1β, and TNF-α are similar to those in atherosclerosis, where TH1 enhances macrophage activation through IFN-γ and IL-2." (PMID 29337902, 2018). "In turn, a sustained increase in the level of IL-6 and TNF-α favors the hepatic release of acute-phase reactants including CRPs, critically involved in PsA, CPs, and atherosclerosis." (PMID 29535705, 2018). "In fact, ICAM-1 together with IL-6, IL8 play an important role in the progression of atherosclerosis through triggering the transendothelial migration of immune cells to the site of inflammation and the activation of pro-inflammatory cascades in target cells." (PMID 30131806, 2018). "Phosphorylation of MAPKs is known to stimulate the mRNA expression of the inflammatory factors such as IL-6, VCAM-I and ICAM-I, and MAPKs of ERK1/2 plays an important role in atherosclerosis." (PMID 29367652, 2018). "FCs immunization down-regulated the expression level of atherosclerosis related pro-inflammatory cytokines, including IFN-γ, MCP-1, and IL-6 and enhanced the lesion stability with a significant increase in TGF-β1 level." (PMID 30687328, 2018). "The raised IL-6 level in CAE is somewhat controversial, since its role in atherosclerosis appears equivocal." (PMID 29337902, 2018). "Several cytokines and chemokines, such as tumor necrosis factor-alpha (TNF-α), interleukin-1β (IL-1β), interleukin-6 (IL-6), and monocyte chemoattractant protein-1 (MCP-1), are important contributors in atherogenesis and atherosclerosis." (PMID 29118465, 2017). "Given that oxLDL plays a key role in all stages of atherosclerosis by regulating the expression of JAB1 and pro-inflammatory cytokines, we showed an oxLDL-induced upregulation of TNF-α and IL-6 mRNA expression and protein secretion in differentiated human MФ." (PMID 28173800, 2017). "In addition, the interleukin-6 gene plays a role in BP regulation and the progression of atherosclerosis in Japanese individuals by stimulating the proliferation of VSMCs, indicating that this cytokine may play an important role in the development of arteriosclerosis." (PMID 29208002, 2017). "IL-6 also promotes vascular SMC proliferation, which is a feature of the early stages of hypertension and atherosclerosis." (PMID 28837559, 2017). "The “inflammatory theory” of atherosclerosis highlights the key role of specific cytokines, particularly tumour necrosis factor-alpha (TNF-α), interleukin-1 (IL-1), and interleukin-6 (IL-6), in disrupting endothelial integrity and vascular homeostasis." (PMID 29430085, 2017). "Several cytokines (e.g. IL1β, IL6, and TNFα) are known to stimulate the expression of ICAM-1 and VCAM-1, two important molecules involved in the development of atherosclerosis." (PMID 27277003, 2016). "It is generally accepted that TNF-α and IL-6 have important role in pathogenesis of T2DM and also atherosclerosis." (PMID 28033351, 2016). "Key factors contributing to early stages of atherosclerosis and plaque development include the pro-inflammatory cytokines Interferon (IFN)α, IFNγ and Interleukin (IL)-6 and Toll-like receptor 4 (TLR4) stimuli." (PMID 27166190, 2016).
atherosclerosis (continued). "IL-6 is a vascular inflammation indicator and activates JAK/STAT3 signalling to promote atherosclerosis development." (PMID 27845432, 2016). "Then, we used the atherogenic stimuli IL-6 and ox-LDL to stimulate cultured cells to assess PIAS3 expression in the setting of atherosclerosis-induced inflammation." (PMID 27845432, 2016). "The pathogenesis of atherosclerosis is connected to dyslipidemia and markers of inflammation (e.g., CRP and IL-6), as well as other cytokines and adhesion molecules which affect endothelial cell activation." (PMID 27527149, 2016). "It was manifested as an increased expression of inflammatory molecules (IL-6 and VCAM-1) and decreased anti-atherosclerosis factor eNOS." (PMID 26890696, 2016). "Interleukin-6, TNF-α, VCAM1, ICAM1 and MCP-1 are important inflammatory cytokines that are engaged in the development of atherosclerosis, which can exacerbate it." (PMID 25661015, 2015). "Herein, we have shown that MED can significantly inhibit the ox-LDL-induced expression of TNF-α, IL-6, and IL-1β both in RAW264.7 cells and in plaque lesion areas, which suggests that MED can suppress inflammatory responses in atherosclerosis." (PMID 26045945, 2015). "The laboratory indices of microinflammation include elevated blood levels of CRP and some cytokines, mainly IL-6, IL-18, IL-10, and TNF-alpha, which correlated with acceleration of atherosclerosis." (PMID 26236736, 2015). "Di(2-ethylhexyl) phthalate (DEHP) has been shown to induce atherosclerosis by increasing tumor necrosis factor (TNF)-α, interleukin (IL)-6, and intercellular adhesion molecule (ICAM) productions." (PMID 26690114, 2015). "Chemokines such as MCP-1, GM-CSF, PDGF-BB, IL-6 and CCL-5 are known to promote atherosclerosis and myocardial ischemia." (PMID 26246800, 2015). "Other important pathways for endothelial homeostasis that were disrupted included inflammatory pathways (for example, atherosclerosis, agranulocyte adhesion and diapedesis) represented by the upregulation of genes such as ICAM1, BMP4 and IL6." (PMID 26617239, 2015). "In accordance with the nature of atherosclerosis as a chronic inflammatory disease, the levels of plasma IFN-γ, TNF-α and IL-6, three major inflammatory biomarkers, were significantly increased in AS patients compared with those in healthy subjects." (PMID 26071079, 2015). "Given the largely known role of IL-6 and PTX-3 as indicators for atherosclerosis, our results (also including the increased carotid IMT in OSA HTN subjects) suggest an additive effect of OSA and hypertension on the progression of endothelial impairment." (PMID 26697221, 2015). "Considering that in atherosclerosis ADAM17 is overactive, IL-6 is expected to present a proinflammatory role in this disease." (PMID 26578976, 2015). "The released NF-κB dimers enter the nucleus and activate the expression of many genes involved in the initiation and progression of atherosclerosis, including cytokines (e.g., TNF, IL-6), adhesion molecules (e.g., VCAM-1, ICAM-1) and chemokines (e.g., MCP-1)." (PMID 26322890, 2015). "IL-6 stimulates hepatic release of CRP and fibrinogen, both acute-phase reactants involved in the process of atherosclerosis and atherothrombosis." (PMID 25000444, 2014). "As a key regulator of atherosclerosis, NF-κB regulates the expressions of various inflammatory factors, including VCAM-1, MCP-1, IL-6 and TNF-α, which in turn accelerate the progress of chronic inflammation." (PMID 24621517, 2014). "LTB4, the downstream metabolite of 5-LOX, increases the mRNA expression of IL-6 and MCP-1 via BLT1 and BLT2, G protein-coupled receptors of leukotrienes, via a NF-κB-dependent mechanism in atherosclerosis." (PMID 25229347, 2014). "This is in agreement with the findings that in atherosclerosis, an inflammatory disease characterized by elevated levels of CRP and IL-6, a low vagal tone is inversely correlated with these inflammatory markers." (PMID 25207649, 2014).